SRGAP1 (SLIT-ROBO Rho GTPase activating protein 1)
Description:
GTPase-activating protein for RhoA and Cdc42 small GTPases. Together with CDC42 seems to be involved in the pathway mediating the repulsive signaling of Robo and Slit proteins in neuronal migration. SLIT2, probably through interaction with ROBO1, increases the interaction of SRGAP1 with ROBO1 and inactivates CDC42.
Synonyms: ARHGAP13; KIAA1304; NMTC2
Tractability: PROTAC: ubiquitination databases record sites on it; its protein half-life has been measured.
Gene: Protein-coding gene on chromosome 12 (63,843,761 to 64,162,217, forward strand). Ensembl gene ENSG00000196935.
Subcellular location (Human Protein Atlas): Cytosol; Basal body; Centrosome
Pathways (Reactome):
Signal Transduction: CDC42 GTPase cycle; RAC1 GTPase cycle; RHOA GTPase cycle
Developmental Biology: Inactivation of CDC42 and RAC1
Gene Ontology:
Molecular function: protein binding; GTPase activator activity; small GTPase binding
Biological process: negative regulation of cell migration; nervous system development; regulation of synapse assembly; signal transduction
Cellular component: cytosol
Genetic constraint (gnomAD): Loss-of-function variants: 34 observed, 96.26 expected, observed/expected ratio (o/e) 0.35, 90% interval 0.27 to 0.47. The upper end of that interval is the gene's LOEUF score, 0.47, which puts it in group 2 of 6, group 1 being the genes least tolerant of losing a copy. Missense variants: 988 observed, 1,248.5 expected, observed/expected ratio (o/e) 0.79, 90% interval 0.75 to 0.83. Synonymous variants: 418 observed, 461.85 expected, observed/expected ratio (o/e) 0.91, 90% interval 0.83 to 0.98.
Homologues: Orthologues: macaque SRGAP1 (100% identical), chimpanzee SRGAP1 (99% identical), dog SRGAP1 (99% identical), guinea pig SRGAP1 (99% identical), rabbit SRGAP1 (99% identical), pig SRGAP1 (98% identical), rat Srgap1 (98% identical), mouse Srgap1 (95% identical), tropical clawed frog srgap1 (91% identical), zebrafish srgap1a (83% identical), Caenorhabditis elegans srgp-1 (29% identical). Paralogues in human: SRGAP3 (69% identical), SRGAP2 (67% identical), ARHGAP4 (39% identical), SRGAP2B (33% identical), SRGAP2C (33% identical).
Diseases named in the same sentence as SRGAP1 in open-access papers:
SRGAP1 is named in the same sentence as 22 diseases in open-access papers, as found by Europe PMC text mining. Sharing a sentence is not in itself a finding about the gene and the disease. The quoted sentences say what the papers report.
dyslexia (2 papers, 2010 to 2021). A learning disorder characterized by an impairment in processing written words. "The six candidate genes sequenced, CNTN1, FOXJ2, GRIN2B, NAB2, NELL2 and SRGAP1, were selected based on their putative functions, and their relationships to genes potentially involved in the pathology of language impairments, auditory processing deficits, autism and dyslexia." (PMID 20345892, 2010). "However, it is not yet clear how SLIT1 and SRGAP1 are directly involved in the development of dyslexia." (PMID 34674647, 2021).
schizophrenia (2 papers, 2013 to 2021). A major psychotic disorder characterized by abnormalities in the perception or expression of reality. "The inverse F-BAR (IF-BAR) domain proteins srGAP1, srGAP2 and srGAP3 are implicated in neuronal development and may be linked to mental retardation, schizophrenia and seizure." (PMID 23505444, 2013).
brain tumor (1 paper, 2012). "By filtering the resulting lists for those targets that were identified by multiple search algorithms, we found a number of potential miR-145 targets (especially srGAP1) in the Slit/Robo pathway, which was recently recognized as an inhibitor of brain tumor cellular migration and invasion." (PMID 22490015, 2012).
lung carcinoma (1 paper, 2010). "Using immunoprecipitation (IP)-Western, we showed that OSU-HDAC-44 increased the interaction between srGAP1 and RhoA in A549 lung cancer cells." (PMID 20856855, 2010).
multicystic dysplastic kidney (1 paper, 2021). Multicystic dysplastic kidney (MCDK) is a congenital anomaly of the kidney and urinary tract (CAKUT) in which one or both kidneys (unilateral or bilateral MCDK respectively) are large, distended by multiple cysts, and non-functional. "Variants in ROBO2, and likely also variants in SLIT2 and the downstream small GTPase activator SRGAP1, lead to CAKUT (mostly multicystic dysplastic kidneys, MCDK) in humans." (PMID 33625646, 2021).
oral cancer (1 paper, 2024). "In addition, several downstream targets of these specific microRNAs were upregulated by all oral cancer cell lines, such as MBTD1 and FSCN1, or downregulated in all cell lines, such as CLCN3, FLI-1, MRTFB, DAB, SRGAP1, and ABHD17C." (PMID 38396844, 2024).
osteosarcoma (1 paper, 2016). A usually aggressive malignant bone-forming mesenchymal neoplasm, predominantly affecting adolescents and young adults. "We evaluated the mRNA expression levels of SRGAP1 in the 12 juvenile osteosarcoma samples and osteoblast controls." (PMID 27966608, 2016).
papillary thyroid carcinoma (1 paper, 2016). "Interestingly, a recent study reported srGAP1 as a candidate susceptibility gene in papillary thyroid carcinoma, and several mutations of srGAP1 identified in papillary thyroid carcinoma resulted in severely impaired ability of srGAP1 to inactivate CDC42." (PMID 27923383, 2016).
cancer (5 papers, 2012 to 2023). A tumor composed of atypical neoplastic, often pleomorphic cells that invade other tissues. "Although srGAP1 plays an important role in tumor progression, little was known about its expression and clinical significance in human cancers, including CRC." (PMID 27923383, 2016). "HTPB may inhibit cancer cell motility partly through reactivation of srGAP1 via promoting histone acetylation of srGAP1 promoter and further attenuation of downstream Rho/FAK/MMP signaling pathway." (PMID 22279574, 2012). "Little was known about the expression and clinical significance of srGAP1 in human cancers, including CRC, so we measured the protein levels of srGAP1 in 156 paired CRC and NCT tissues by IHC staining." (PMID 27923383, 2016). "Whether srGAP1-Cdc42 axis is a key downstream functional target of Slit2 signaling in CRC remains to be elucidated and little was known about the expression and clinical significance of srGAP1 in human cancer." (PMID 27923383, 2016).
tumor (5 papers, 2013 to 2023). "In summary, our data revealed that the downregulation of srGAP1 in CRC tissues is associated with tumor progression and poor prognosis, and srGAP1-Cdc42 regulatory axis is a key downstream target of Slit2-Robo1 pathway in CRC." (PMID 27923383, 2016). "Downregulation of srGAP1 in CRC was associated with tumor progression and poor prognosis." (PMID 27923383, 2016). "Noticeably, srGAP1 expression in CRCs was significantly correlated with tumor differentiation (Spearman r = −0.162, P = 0.044), lymphatic invasion (Spearman r = −0.194, P = 0.015) and TNM stage (Spearman r = −0.202, P = 0.011), suggesting that srGAP1 expression was associated with tumor progression." (PMID 27923383, 2016). "miR-214 suppressed tumor development by targeting the oncogene Slit-Robo Rho GTPase-activating protein 1 (SRGAP1)." (PMID 35656022, 2022). "In this study, we confirmed that srGAP1 binds to Robo1 in responding to the Slit2 treatment and mediates its tumor suppressive function in CRC." (PMID 27923383, 2016). "In this study, we revealed that srGAP1 is significantly downregulated in CRC tissues, and was associated with tumor progression and survival." (PMID 27923383, 2016). "Decreased expression of srGAP1 in CRC tissues was associated with several key features of tumor aggression and progression, including lymphatic invasion, tumor differentiation and TNM stage." (PMID 27923383, 2016). "Clinical sample analyses revealed that srGAP1 was significantly downregulated in CRC tissues, which was associated with tumor progression and poor patient survival." (PMID 27923383, 2016). "Collectively, these data suggest the tumor suppressive role of srGAP1 in CRC." (PMID 27923383, 2016). "The protein expression of srGAP1 was remarkably decreased in 47.5% of CRC tissues compared with adjacent noncancerous tissues, and the decreased srGAP1 expression was associated with lymphatic invasion, poor tumor differentiation, high TNM stage, and poor survival (P < 0.05)." (PMID 27923383, 2016). "The function of FBN3, PCNXL3, SFXN3, SRGAP1, VN1R5 and WDR70 have been only marginally evaluated, and their role in the molecular signaling of tumor cells remains largely understudied." (PMID 23577124, 2013). "After adjusting for nodal status, tumor differentiation and TNM stage, multivariate analyses revealed that patients with high srGAP1 expression show a trend of prolonged survival time as compared to patients with low srGAP1 expression (HR = 0.613; 95% CI, 0.360–1.041, P = 0.070)." (PMID 27923383, 2016).
infection (1 paper, 2017). The state of being infected such as from the introduction of a foreign agent such as serum, vaccine, antigenic substance or organism. "Secondly, infection of the two cell lines with MEG3-overexpression lentivirus resulted in increased MEG3 expression levels, whereas SRGAP1 expression was downregulated at the mRNA and protein levels." (PMID 29050236, 2017).
kidney diseases (1 paper, 2021). "In addition to Arhgap24, Srgap1, and the other GTPase-activating proteins, other genes involving small GTPase-mediated pathways may also mediate miR-145-5p-induced podocyte injury (e.g., PLCE1, which mutations have been shown to cause podocyte injury and kidney diseases)." (PMID 34729245, 2021).
SRGAP1 also shares sentences with these, for which no sentence is quoted: colorectal cancer (2 papers); autism (1); focal segmental glomerulosclerosis (1); germinal matrix hemorrhage (1); hearing loss (1); hyperlipidemia (1); neurodegenerative disease (1); Obesity (1); Sepsis (1); thyroid cancer (1).